NOP56 (NOP56 ribonucleoprotein)
Description:
Involved in the early to middle stages of 60S ribosomal subunit biogenesis. Required for the biogenesis of box C/D snoRNAs such U3, U8 and U14 snoRNAs. Part of the small subunit (SSU) processome, first precursor of the small eukaryotic ribosomal subunit. During the assembly of the SSU processome in the nucleolus, many ribosome biogenesis factors, an RNA chaperone and ribosomal proteins associate with the nascent pre-rRNA and work in concert to generate RNA folding, modifications, rearrangements and cleavage as well as targeted degradation of pre-ribosomal RNA by the RNA exosome. Core component of box C/D small nucleolar ribonucleoprotein (snoRNP) complexes that function in methylation of multiple sites on ribosomal RNAs (rRNAs) and messenger RNAs (mRNAs).
Synonyms: NOL5A; SCA36
Tractability: Small molecule: a structure with a bound ligand is known. PROTAC: UniProt records ubiquitination sites on it; ubiquitination databases record sites on it; its protein half-life has been measured.
Gene: Protein-coding gene on chromosome 20 (2,652,592 to 2,658,393, forward strand). Ensembl gene ENSG00000101361.
Subcellular location: Nucleus, nucleolus; Cytoplasm; Nucleus, nucleoplasm
Subcellular location (Human Protein Atlas): Nucleoli fibrillar center
Pathways (Reactome):
Metabolism of RNA: Major pathway of rRNA processing in the nucleolus and cytosol; rRNA modification in the nucleus and cytosol
Metabolism of proteins: Association of TriC/CCT with target proteins during biosynthesis
Gene Ontology:
Molecular function: cadherin binding; histone methyltransferase binding; protein binding; RNA binding; snoRNA binding
Biological process: ribosomal small subunit biogenesis; maturation of SSU-rRNA; mRNA modification; neuron differentiation; rRNA 2'-O-methylation; rRNA processing
Cellular component: box C/D methylation guide snoRNP complex; fibrillar center; membrane; nucleolus; pre-snoRNP complex; small-subunit processome; sno(s)RNA-containing ribonucleoprotein complex; nucleoplasm; cytoplasm
Genetic constraint (gnomAD): Loss-of-function variants: 32 observed, 59.48 expected, observed/expected ratio (o/e) 0.54, 90% interval 0.41 to 0.72. The upper end of that interval is the gene's LOEUF score, 0.72, which puts it in group 2 of 6, group 1 being the genes least tolerant of losing a copy. Missense variants: 663 observed, 762.31 expected, observed/expected ratio (o/e) 0.87, 90% interval 0.81 to 0.93. Synonymous variants: 312 observed, 292.3 expected, observed/expected ratio (o/e) 1.07, 90% interval 0.97 to 1.17.
Homologues: Orthologues: chimpanzee NOP56 (99% identical), macaque NOP56 (99% identical), dog NOP56 (94% identical), pig NOP56 (93% identical), guinea pig NOP56 (92% identical), rabbit NOP56 (92% identical), rat Nop56 (90% identical), mouse Nop56 (89% identical), tropical clawed frog nop56 (68% identical), zebrafish nop56 (67% identical), Caenorhabditis elegans nol-56 (47% identical). Paralogues in human: NOP58 (37% identical).
Diseases named in the same sentence as NOP56 in open-access papers:
NOP56 is named in the same sentence as 41 diseases in open-access papers, as found by Europe PMC text mining. Sharing a sentence is not in itself a finding about the gene and the disease. The quoted sentences say what the papers report.
Ataxia (12 papers, 2018 to 2025). Ataxia refers to impaired coordination of voluntary muscle movement. "Expansion of intronic GGCCTG hexanucleotide repeat in NOP56 causes SCA36, a type of spinocerebellar ataxia accompanied by motor neuron involvement." (PMID 38664915, 2024). "One report in 2017 found that four out of 577 (0.7%) of undiagnosed ataxia is caused by GGCCTG repeats in the Nop56 gene, and the origins were shown to be from European, Japanese, and Vietnamese ancestors." (PMID 35309140, 2022). "We analyzed the expression pattern of 28 ataxia risk genes and found that majority of them are highly expressed in PCs, while only a few of them, including elongation factor 2 (Eef2), ataxin-10 (Atxn10), nucleolar protein 56 (Nop56), are widely expressed in all cell types." (PMID 30690467, 2019). "Protein coding genes proximal to these snoRNAs were implicated in several neurologic conditions, including Wernicke‐Korsakoff Syndrome (Tex2/SNORD104), Spinocerebellar Ataxia (Nop56/SNORD57), and Parkinson Disease (EIF4A2/SNORD2)." (PMID 33135344, 2020). "This study involved six genes (ATXN1, ATXN3, ATXN7, HTT, NOP56, and PPP2R2B), while a higher detection rate has been reported in a spinocerebellar ataxia cohort (4.4%, 22/498), which included five genes (ATXN2, ATXN3, NOP56, AR and HTT)." (PMID 38308084, 2024).
amyotrophic lateral sclerosis (9 papers, 2014 to 2025). Amyotrophic lateral sclerosis (ALS) is a neurodegenerative disease characterized by progressive muscular paralysis reflecting degeneration of motor neurons in the primary motor cortex, corticospinal tracts, brainstem and spinal cord. "C9orf72, fus and tardbp genes, related to Amyotrophic Lateral Sclerosis (ALS), also had reduced mRNA expression in nop56 homozygous mutants." (PMID 36009362, 2022).
spinocerebellar ataxia 36 (4 papers, 2022 to 2026). "Pathogenic variants in ZNHIT3 (MIM: 604500) and NOP56 (MIM: 614154) cause the progressive encephalopathy with edema, hypsarrhythmia, and optic atrophy (PEHO) syndrome (MIM: 260565) and spinocerebellar ataxia 36 (SCA36 [MIM: 614153]), respectively." (PMID 41383020, 2026). "Conversely, UTR and intronic loci, such as DMPK and NOP56 (myotonic dystrophy type 1 and spinocerebellar ataxia 36), have higher genotyping rates across all exome capture kits analysed." (PMID 40004498, 2025). "Spinocerebellar Ataxia type 36 (SCA36), also known as “Costa da Morte ataxia” and “Asidan ataxia”, is caused by a heterozygous expansion of the “GGCCTG” repeats within NOP56 intron (referred as “SCA36 expansion” throughout the text)." (PMID 36009362, 2022).
breast carcinoma (2 papers, 2017 to 2025). "NOP56 is overexpressed in several cancers, such as lung adenocarcinoma, acute lymphoblastic leukemia, and breast cancer." (PMID 41568368, 2025).
colorectal cancer (2 papers, 2025 to 2026). A primary or metastatic malignant neoplasm that affects the colon or rectum. "Nucleolar protein 56 (NOP56), a core component of small nucleolar ribonucleoprotein complexes, has been implicated in oncogenesis through the regulation of reactive oxygen species (ROS) homeostasis; however, its role in colorectal cancer (CRC) remains unclear." (PMID 42157947, 2026).
acute myeloid leukaemia (1 paper, 2022). "NOP56 has been shown to be upregulated in acute myeloid leukaemia and may also be associated with poorer outcome." (PMID 35054812, 2022).
anemia (1 paper, 2023). A reduction in the number of red blood cells, the amount of hemoglobin, and/or the volume of packed red blood cells. "A nop56 deficiency induced severe morphological abnormalities and anemia." (PMID 37106740, 2023). "Nop56 deficiency induced severe morphological abnormalities and anemia in zebrafish." (PMID 37106740, 2023). "A Nop56 deficiency in zebrafish led to severe anemia and morphological abnormalities." (PMID 37106740, 2023). "Furthermore, both the morphological defects and anemia were mostly rescued by injection with in vitro-transcribed nop56 mRNA in the mutant embryos." (PMID 37106740, 2023). "The combined data from the nop56-deficient zebrafish provide a model in which nop56 is essential for erythropoiesis in zebrafish, although no anemia cases have been reported to be related to a nop56 mutation." (PMID 37106740, 2023).
B-cell precursor acute lymphoblastic leukemia (1 paper, 2021). "Recent study shows that NOP56 overexpression is an antecedent event in the relapse of B-cell precursor acute lymphoblastic leukemia, and it has been shown to be a potential prognostic marker for metastatic renal cell carcinoma." (PMID 34257558, 2021).
Burkitt lymphoma (1 paper, 2016). A rare form of malignant mature B-cell non-Hodgkin lymphoma. "A recent study on Burkitt's lymphoma implicated Nol5a/Nop56 in oncogenesis." (PMID 27602772, 2016).
diffuse large B-cell lymphoma (1 paper, 2023). "The expression of NOP56 is significantly upregulated in acute myeloid leukemia, diffuse large B-cell lymphoma, and Myc-mutant Burkitt’s lymphoma, and may also be associated with poorer prognosis." (PMID 36741964, 2023). "Interestingly, NOP56 expression was significantly downregulated in diffuse large B-cell lymphoma cell lines resistant to adriamycin (Pfeiffer/ADM) compared with diffuse large B-cell lymphoma cell lines (Pfeiffer)." (PMID 36741964, 2023).
liver cancer (1 paper, 2024). An epithelial or non-epithelial malignant neoplasm that arises from the liver. "We propose that before the recognized oncogenic pathways are activated, four key DEGs (BMI1, NOP56, UBE2E1, and FAM98A) are aberrantly expressed, revealing the different prognoses of patients with liver cancer." (PMID 38515119, 2024).
Lordosis (1 paper, 2022). "Lordosis was first observed at 48 hpf in 40% of nop56−/−, at 120 hpf the number rises to 50% of the larvae (less than 5% of the wild type and nop56+/− had this malformation at this developmental stage)." (PMID 36009362, 2022).
lung carcinoma (1 paper, 2022). "Thus, targeting NOP56 disrupts ROS homeostasis and induces IRE1α-mediated UPR in KRAS-mutant lung cancer cells." (PMID 35039048, 2022).
lymphoma (1 paper, 2022). A malignant (clonal) proliferation of B- lymphocytes or T- lymphocytes which involves the lymph nodes, bone marrow and/or extranodal sites. "The HPA database results showed that the protein levels of TSR1, WDR46, HSP90AA1, and NOP56 in lymphoma were higher than those in normal lymphoid tissue, whereas the protein level of UBC in lymphoma was lower than that in normal lymphoid tissue." (PMID 35263200, 2022).
melanoma (1 paper, 2018). A malignant, usually aggressive tumor composed of atypical, neoplastic melanocytes. "Nop56 and Ebna1bp2 also interacted with Csde1 in melanoma cells." (PMID 29422612, 2018).
thyroid cancer (1 paper, 2025). "We have shown that pY397 FAK is localized in the nucleolus in aggressive thyroid cancer cells where it interacts with nucleolar proteins involved in ribosomal biogenesis including NOP56, TOP1, RPL36, and PRKDC." (PMID 40458728, 2025). "Finally, we showed that a fraction of pY397 FAK co-localizes with NOP56, a key regulator of 60S ribosome biogenesis, and that NOP56 is important for thyroid cancer growth and survival." (PMID 40458728, 2025).
cancer (9 papers, 2016 to 2025). A tumor composed of atypical neoplastic, often pleomorphic cells that invade other tissues. "Nucleolar protein 56 (NOP56) is an essential component in ribosome biogenesis while its overexpression associates with various types of cancers, rendering it a significant therapeutic target." (PMID 40047221, 2025). "To highlight their relevance in cancer, we interrogated the HumanNet v3 and found that NOP56, RBM12, FKBP1A and EMG1 are highly interconnected with cancer genes and other RBPs, showing their potential to form tumorigenic RNA-regulons." (PMID 37384253, 2023). "This is supported by the DDX11, DKC1, EXOSC5, NOP56, and other genes showing differences in the most cancer types." (PMID 36698399, 2022). "In summary, we analyzed and integrated data from 488 COAD and 155 READ patients, 102 cancer cell lines, more than 15,000 immunostainings, and ∼10,000 raw associations between RBPs and cancer genes to unravel new RBPs involved in COAD (NOP56, NAT10, RBM12, and FKBP1A) and READ (EMG1 and CSE1L)." (PMID 37384253, 2023).
tumor (8 papers, 2016 to 2025). "In COAD, we identified two RBPs (NAT10 and NOP56) having all four tumor-associated characteristics presented in this study." (PMID 37384253, 2023). "Growing evidence suggests that nucleolar proteins such as NOP56 influence tumor progression not only through ribosome biogenesis but also by regulating cellular stress responses and oncogenic signaling pathways." (PMID 41568368, 2025). "In conclusion, our study identifies NOP56 as an oncogenic nucleolar protein in HCC that drives tumor progression through interaction with FBL and activation of the PI3K/AKT/CREB pathway." (PMID 41568368, 2025). "NOP56 knockdown inhibited proliferation, colony formation, and migration, induced G0/G1 arrest and apoptosis, and reduced tumor growth in vivo." (PMID 41568368, 2025). "Reduced expression of NOP56 will severely inhibit tumor cell proliferation and promote tumor cell death." (PMID 36741964, 2023). "The genes coding for Nol5a/Nop56 were highly significantly up-regulated in PLACs and Nol5a was shown to be necessary for c-Myc-induced cell transformation and tumor growth." (PMID 27602772, 2016). "Immunohistochemical staining further confirmed the elevated expression of NOP56 in tumor samples." (PMID 41568368, 2025). "However, the outcome of concomitant targeting of NOP56 and mTOR (shNOP56 plus rapamycin) was superior to that achieved by shNOP56 or rapamycin alone, leading to far more effective and potent suppression of xenograft tumor growth." (PMID 35039048, 2022). "In this study, we identified the nucleolar protein NOP56 as a novel oncogenic factor in HCC, promoting tumor growth by regulating proliferation, migration, cell cycle progression, and apoptosis." (PMID 41568368, 2025). "In humans, the expression of SLC12A2, FERMT1, NCL, NOP56, and NOXA1 was significantly upregulated in human tumor cells compared to that in normal controls." (PMID 38886341, 2024). "The expression levels of mRNA and proteins of TSR1, WDR46, HSP90AA1, and NOP56 in DLBCL were significantly higher than those in normal tissues, suggesting that these four hub genes can be activated and can upregulate the expression of mRNA during tumor development." (PMID 35263200, 2022).
NOP56 also shares sentences with these, for which no sentence is quoted: frontotemporal dementia (4 papers); fragile X-associated tremor/ataxia syndrome (3); Friedreich ataxia (3); cerebellar ataxia (2); myotonic dystrophy type 1 (2); Parkinson disease (2); spinocerebellar ataxia type 31 (2); Alzheimer disease (1); dentatorubral-pallidoluysian atrophy (1); essential tremor (1); Fuchs endothelial corneal dystrophy (1); hepatocellular carcinoma (1); hereditary cerebellar ataxia (1); Huntington disease (1); Huntington disease-like 2 (1); Machado-Joseph disease (1); movement disorder (1); myotonic dystrophy type 2 (1); neuroblastoma (1); neurodegenerative disease (1); neurological diseases (1); neuronal intranuclear inclusion disease (1); Parkinsonism (1).